HSD17B12 (hydroxysteroid 17-beta dehydrogenase 12)
Description:
Catalyzes the second of the four reactions of the long-chain fatty acids elongation cycle. This endoplasmic reticulum-bound enzymatic process, allows the addition of two carbons to the chain of long- and very long-chain fatty acids/VLCFAs per cycle. This enzyme has a 3-ketoacyl-CoA reductase activity, reducing 3-ketoacyl-CoA to 3-hydroxyacyl-CoA, within each cycle of fatty acid elongation. Thereby, it may participate in the production of VLCFAs of different chain lengths that are involved in multiple biological processes as precursors of membrane lipids and lipid mediators. May also catalyze the transformation of estrone (E1) into estradiol (E2) and play a role in estrogen formation.
Synonyms: KAR; SDR12C1
Tractability: Antibody: UniProt predicts a signal peptide or a membrane-spanning region; its Gene Ontology location is reachable by antibodies, with medium confidence. PROTAC: ubiquitination databases record sites on it; its protein half-life has been measured.
Target class: Enzyme; Oxidoreductase
Gene: Protein-coding gene on chromosome 11 (43,680,509 to 43,857,741, forward strand). Ensembl gene ENSG00000149084.
Subcellular location: Endoplasmic reticulum membrane
Pathways (Reactome):
Metabolism: Androgen biosynthesis; Synthesis of very long-chain fatty acyl-CoAs
Gene Ontology:
Molecular function: estradiol 17-beta-dehydrogenase [NAD(P)+] activity; protein binding; very-long-chain 3-oxoacyl-CoA reductase activity; acetoacetyl-CoA reductase activity; collagen binding; fibronectin binding; heparin binding; oxidoreductase activity, acting on CH-OH group of donors; testosterone dehydrogenase (NADP+) activity
Biological process: fatty acid elongation, saturated fatty acid; long-chain fatty-acyl-CoA biosynthetic process; androgen biosynthetic process; estrogen biosynthetic process; fatty acid biosynthetic process; lipid biosynthetic process
Cellular component: endoplasmic reticulum membrane; fatty acid elongase complex; endoplasmic reticulum; extracellular matrix
Genetic constraint (gnomAD): Loss-of-function variants: 9 observed, 11.97 expected, observed/expected ratio (o/e) 0.75, 90% interval 0.45 to 1.31. The upper end of that interval is the gene's LOEUF score, 1.31, which puts it in group 5 of 6, group 1 being the genes least tolerant of losing a copy. Missense variants: 162 observed, 186.85 expected, observed/expected ratio (o/e) 0.87, 90% interval 0.76 to 0.99. Synonymous variants: 83 observed, 84.67 expected, observed/expected ratio (o/e) 0.98, 90% interval 0.82 to 1.18.
Homologues: Orthologues: chimpanzee HSD17B12 (99% identical), macaque HSD17B12 (96% identical), rabbit HSD17B12 (87% identical), dog HSD17B12 (86% identical), pig HSD17B12 (82% identical), rat Hsd17b12 (82% identical), mouse Hsd17b12 (81% identical), guinea pig HSD17B12 (81% identical), tropical clawed frog hsd17b12 (62% identical), zebrafish hsd17b12b (60% identical), zebrafish hsd17b12a (59% identical). Paralogues in human: HSDL1 (41% identical), HSD17B3 (40% identical), BDH1 (24% identical), HSD17B13 (23% identical), RDH16 (21% identical), HSD17B6 (21% identical), HSD17B11 (20% identical), SDR16C5 (20% identical), DHRS3 (20% identical), SDR9C7 (20% identical), HSD17B2 (19% identical), RDH5 (19% identical), and 13 more.
Diseases named in the same sentence as HSD17B12 in open-access papers:
HSD17B12 is named in the same sentence as 42 diseases in open-access papers, as found by Europe PMC text mining. Sharing a sentence is not in itself a finding about the gene and the disease. The quoted sentences say what the papers report.
breast carcinoma (7 papers, 2013 to 2025). "Overexpression of HSD17B12 was recently associated with COX2 (1q31) overexpression in breast carcinomas, and in our cohort, HSD17B12 gains were detected in association with COX2 gains, which may indicate a new 1q31/11p11 co-amplification pattern in ER-negative high-grade breast tumors." (PMID 25391423, 2015). "Additionally, interfering HSD17B12 inhibited the growth of breast cancer cells, whereas supplementation with arachidonic acid completely restored growth." (PMID 37834341, 2023). "These were Estrogen Biosynthesis (HSD17B7 and HSD17B12), Estrogen-Dependent Breast Cancer Signaling (HSD17B7 and HSD17B12), Hepatic Fibrosis/Hepatic Stellate Activation (CD14 and CD40), Tight Junction Signaling (CDSF1 and OCLN), and Dopamine-DARPP32 Feedback in cAMP Signaling (CACNAID and CSNK1E)." (PMID 23759029, 2013). "Moreover, interference with HSD17B12 expression inhibits the proliferation of breast cancer cells." (PMID 37834341, 2023).
neuroblastoma (6 papers, 2016 to 2025). Neuroblastoma (NB) is the most common solid, extracranial childhood tumor. "Through integrative genomic analysis of SNPs at the 11p11.2 locus, we focused on the variant rs2863002 T>C within HSD17B12, which emerged as a key regulatory element in neuroblastoma." (PMID 40525640, 2025). "We demonstrated that the C risk allele correlates with increased expression of the target gene HSD17B12 in the adrenal gland tissue and in a set of neuroblastoma patients with the homozygous risk genotype." (PMID 40525640, 2025). "By a combination of genome editing experiments and functional validation of the lipidomic results, we demonstrated that the altered lipid metabolism in neuroblastoma cells was likely mediated by the risk SNP rs2863002 via modulation of HSD17B12 expression." (PMID 40525640, 2025). "Collectively, these results robustly sustain the contribution of the genetic variant rs2863002 and its regulatory effect on HSD17B12 to the oncogenic process in neuroblastoma." (PMID 40525640, 2025). "Conversely, in CRISPR/Cas9‐edited clones with alterations of the rs2863002 region, there was a marked increase in the quantity and size of lipid droplets, further emphasizing the influence of the neuroblastoma risk variant rs2863002 on HSD17B12 functionality." (PMID 40525640, 2025). "The upregulation of genes BSG/CD147, CCDC125, GABRB3, GNB2L1/RACK1, HAPLN4, HEBP2, and HSD17B12 is associated with poor neuroblastoma prognosis and low EFS." (PMID 38398114, 2024). "Later on, the same group reported that common variants in BARD1 gene were associated with high-risk neuroblastoma, and polymorphisms within DUSP12, DDX4, IL31RA, and HSD17B12 were associated with low-risk neuroblastoma." (PMID 31341530, 2019). "The identification of HSD17B12 as a novel neuroblastoma susceptibility gene involved in lipid metabolism suggests it could serve as a biomarker for risk stratification and a potential therapeutic target." (PMID 40525640, 2025). "HSD17B12 has been established as a gene of oncological importance across diverse tumor types through numerous GWASs, with associations observed in cutaneous melanoma, prostate, colorectal, and oral cancer, but its functional role in neuroblastoma was unexplored." (PMID 40525640, 2025). "Silencing of HSD17B12 led to a marked decrease in cell proliferation and invasiveness in both neuroblastoma cell lines compared to control conditions." (PMID 40525640, 2025). "They highlight that this SNP modulates HSD17B12 expression, promoting oncogenic activity in neuroblastoma by significantly enhancing tumor cell proliferation and invasiveness." (PMID 40525640, 2025). "Overexpression of HSD17B12 promotes a pro‐tumorigenic phenotype in neuroblastoma cells and leads to alterations in lipid metabolism." (PMID 40525640, 2025). "In vitro functional assays and targeted lipidomic analyses reveal the involvement of the rs2863002‐C risk allele in tumorigenicity and modulation of lipid metabolism in neuroblastoma cells through HSD17B12 regulation." (PMID 40525640, 2025). "Taken together, these findings show that the silencing of HSD17B12 has a wide impact on many cellular lipid class molecules, thus affirming an important regulatory role of HSD17B12 in the metabolism of LCFAs within neuroblastoma." (PMID 40525640, 2025). "Our investigation of lipid metabolism following the silencing of HSD17B12 or genome editing on the rs2863002 SNP revealed a significant impact on the lipid profiles and downregulation of key lipid molecules in these in vitro neuroblastoma cellular models." (PMID 40525640, 2025). "In this study, we provide a list of additional candidate regulatory SNPs that may influence HSD17B12 or other target genes, potentially contributing to neuroblastoma development." (PMID 40525640, 2025). "Additionally, we demonstrated that suppression of HSD17B12 in neuroblastoma cell models significantly reduces tumor cell growth and invasiveness." (PMID 40525640, 2025).
neuroblastoma (continued). "In exploring the potential oncogenic role of HSD17B12 in neuroblastoma, we examined its expression in the context of prognostic factors using the extensive RNA‐seq database SEQC (GSE62564), encompassing 498 neuroblastoma tumor samples." (PMID 40525640, 2025). "To further confirm the pro‐tumoral activity of HSD17B12, we conducted in vitro tumorigenic assays after applying RNA interference by siRNA transient transfection to diminish HSD17B12 expression in the SH‐SY5Y and NMB neuroblastoma cells." (PMID 40525640, 2025).
ovarian carcinoma (5 papers, 2020 to 2024). A malignant neoplasm originating from the surface ovarian epithelium. "Accordingly, HSD17B12 upregulation is associated with poor prognosis of ovarian cancer." (PMID 38398114, 2024). "Furthermore, HSD17B12 is a marker of poor prognosis in ovarian carcinoma and it is also associated with cutaneous melanoma." (PMID 35884374, 2022). "HSD17B12 is also gradually up‐regulated with the severity of ovarian cancer." (PMID 33118286, 2020). "Moreover, the patients with the overexpression of HSD17B12 have worse OS and PFS than those with low expression in ovarian cancer." (PMID 33118286, 2020).
type 2 diabetes (5 papers, 2020 to 2023). "Of note, based on the posterior probability, only HSD17B12, R11-613D13.10 shared causal variants with type 2 diabetes." (PMID 35568807, 2022). "An integrative phenotype–genotype approach using phenotypic characteristics from the UAE national diabetes study identifies HSD17B12 as a candidate gene for obesity and type 2 diabetes." (PMID 36678240, 2023). "RNA-seq analysis revealed high expression levels of HSD17B12 in human islets and to be upregulated in type 2 diabetes (T2D) donors." (PMID 32340285, 2020). "The module related to type 2 diabetes contains three genes with significant P-values (THADA, PTPLA, HSD17B12) and three with P < .05." (PMID 37860106, 2023).
diabetes (4 papers, 2020 to 2025). "Additionally, rs1061810 was documented to be associated with T2D indicating a role for HSD17B12 in diabetes." (PMID 32340285, 2020). "Genes that showed decreased expression with diabetes-risk alleles included CEP68 (rs2052261-A, rs2249105-A), HSD17B12 (rs1061810-A) and the long non-coding RNA (lncRNA) RP11-613D13.10 (rs1061810-A)." (PMID 35568807, 2022).
Obesity (4 papers, 2018 to 2023). Accumulation of substantial excess body fat. "Five variants were top weighted (above the threshold of 0.75) in more than one cluster: CDC123/CAMKID (Beta Cell and Proinsulin), HSD17B12 (Beta Cell and Obesity), ADCY5 (Beta Cell and Lipodystrophy), CCND2 (Proinsulin and Lipodystrophy), and HNF4A (Beta Cell and Proinsulin)." (PMID 30240442, 2018).
benign breast neoplasms (3 papers, 2015 to 2025). "Phenome‐wide MR analysis indicated that CALCRL is correlated with benign breast neoplasms, and HSD17B12 is associated with essential hypertension and hypertension." (PMID 40923186, 2025). "Studies have shown that HSD17B12 mRNA expression level is higher in breast tumour tissues than in normal tissues and negatively correlated with prognosis." (PMID 33118286, 2020). "In our cohort, we detected HSD17B12 gains in association with gains of the COX2 gene, in a possible 1q31/11p11 co-amplification pattern, here observed in ER-negative high-grade breast tumors." (PMID 25391423, 2015). "We identified three new focal rearrangements in grade III/LVI-positive breast tumors: 4q13 and 11q11 amplifications (harboring the ADAMTS3 and the HSD17B12 genes, respectively) and a homozygous deletion at 12p12.3 (containing, among others, the RERGL gene)." (PMID 25391423, 2015). "Additionally, we assembled a panel of genes exhibiting differences in the frequency of copy number changes between high-grade and low-grade breast tumors groups, including two of those genes here reported (RERGL and HSD17B12)." (PMID 25391423, 2015).
cutaneous melanoma (3 papers, 2020 to 2025). A primary melanoma arising from atypical melanocytes in the skin. "HSD17B12 rs11037684 A>G is associated with poor OS in patients with cutaneous melanoma." (PMID 33118286, 2020).
colon cancer (2 papers, 2017 to 2026). "We first confirmed that HSD17B12 negatively regulates PD-L1 expression in CT26 murine colon cancer cells." (PMID 41592073, 2026). "Furthermore, co-immunoprecipitation confirmed the interaction between HSD17B12 and PD-L1 in HEK293T cells, RKO colon cancer cells, and MDA-MB-231 triple-negative breast cancer cells." (PMID 41592073, 2026).
colorectal cancer (2 papers, 2020 to 2026). A primary or metastatic malignant neoplasm that affects the colon or rectum. "Notably, we found a significant negative correlation between HSD17B12 and PD-L1 expression in colorectal cancer tissues." (PMID 41592073, 2026).
prostate carcinoma (2 papers, 2020 to 2021). A carcinoma that arises from epithelial cells of the prostate gland. "Genetic variants in HSD17B12 are associated with a high risk of recurrence in prostate cancer." (PMID 33118286, 2020). "In addition, FASN inactivation with siRNA in LNCaP cells reduces pseudopodia and invadopodia formation, cell adhesion, migration and invasion, and FASN inhibition negatively regulates PLA2G4A and HSD17B12 in several prostate cancer cell lines." (PMID 33166087, 2021). "Finally, FASN inhibition negatively regulates cytosolic phospholipase A2 (PLA2G4A) and estradiol 17‐beta‐dehydrogenase 12 (HSD17B12) in several prostate cancer cell lines." (PMID 33166087, 2021).
Alzheimer disease (1 paper, 2020). A progressive, neurodegenerative disease characterized by loss of function and death of nerve cells in several areas of the brain leading to loss of cognitive function such as memory and language. "Sleep start is also associated with one SNP at gene CYP7B1 related to BMI, two SNPs near gene HSD17B12 related to BMI, two SNPs near MIR129-2 also related to BMI and Alzheimer’s Disease, and two SNPs near LOC101928944 related to schizophrenia." (PMID 33075057, 2020).
cerebrovascular diseases (1 paper, 2025). "Functional validation in knockout mouse models showed HSD17B12’s role in fatty acid metabolism, linking it to cerebrovascular diseases." (PMID 40777745, 2025).
dyslipidemia (1 paper, 2025). "For example, the involvement of HSD17B12 in lipid regulation may facilitate the identification of dyslipidemia-associated stroke risk, potentially enabling early intervention strategies even before clinical manifestations emerge." (PMID 40777745, 2025).
essential hypertension (1 paper, 2025). Hypertension that presents without an identifiable cause. "Similarly, elevated levels of HSD17B12 were associated with decreased risks of essential hypertension (OR: 0.721; 95% CI: 0.629–0.826) and hypertension (OR: 0.728; 95% CI: 0.635–0.834)." (PMID 40923186, 2025).
gall bladder carcinoma (1 paper, 2022). "The top ten cell lines where HSD17B12 is mostly expressed are: mast cells, the gall bladder carcinoma cells, smooth muscle cells from the aorta, mesenchymal stem cells, macrophages, adipocytes from two different donors, melanocytes, fibroblasts from aortic adventitial and fibroblasts from skin." (PMID 35884374, 2022).
melanoma (1 paper, 2026). A malignant, usually aggressive tumor composed of atypical, neoplastic melanocytes. "Immunofluorescence also revealed partial colocalization of PD-L1 and HSD17B12 in A375 melanoma cells and MDA-MB-231 cells." (PMID 41592073, 2026).
ovarian failure (1 paper, 2023). "Additionally, the HSD17B12 enzyme is crucial for ovarian health and its decreased expression can result in early ovarian failure and ovulation problems." (PMID 36771459, 2023).
Premature ovarian insufficiency (1 paper, 2024). Amenorrhea due to loss of ovarian function before the age of 40. "A previous study suggested that an insufficient dose of HSD17B12 affects the fertility of female mice, resulting in premature ovarian insufficiency." (PMID 39518882, 2024).
virus infection (1 paper, 2020). "Interestingly, literature mining supports that HSD17B12 constitutes a hub protein that interacts with proteins of different RNA and DNA viruses, which underline a potential broad-spectrum role of HSD17B12 during viral infections." (PMID 32132633, 2020). "To get an insight into the role of HSD17B12 in virus infection, we first evaluated the impact of HSD17B12 knockdown (KD) on cell toxicity by transducing Huh7.5 cells with lentiviruses expressing short hairpin RNA (shRNA) specific to HSD17B12 or a non-targeting sequence (NT)." (PMID 32132633, 2020).
cancer (13 papers, 2015 to 2026). A tumor composed of atypical neoplastic, often pleomorphic cells that invade other tissues. "Genetic variants in HSD17B12 have been investigated in several cancers." (PMID 33118286, 2020). "However, the enzyme’s mechanism in tumorigenesis is unknown; several studies have reported an association between HSD17B12 expression and cancer outcomes." (PMID 36970499, 2023). "Collectively, our findings highlight HSD17B12’s role in tumor immunity and position it as a promising target for cancer therapy." (PMID 41592073, 2026). "Collectively, these findings demonstrate that the HSD17B12-derived peptide effectively down-regulates PD-L1 and suppresses tumor progression in vivo, suggesting the potential of HSD17B12 as a novel therapeutic target for cancer." (PMID 41592073, 2026). "Overall, our results establish HSD17B12 as an important regulator of anti-tumor immunity and a promising therapeutic target for cancer treatment." (PMID 41592073, 2026). "To investigate the impact of HSD17B12 on PD-L1, we designed distinct shRNAs to knockdown HSD17B12 in various human cancer cell lines (see Materials and methods for shRNA sequences)." (PMID 41592073, 2026). "When HSD17B12 was knocked down in cancer cells with high expression of HSD17B12, cell growth was significantly inhibited with reduced total amounts of FAs and arachidonic acid." (PMID 36970499, 2023). "We found that the expression of HSD17B12 in CRC tissues was the highest among those in the pan‐cancer tissues." (PMID 33118286, 2020). "Contrary to Savolainen-Peltonen, we found that HSD17B12 mRNA expression is higher in adipose tissue from cancer patients than in controls." (PMID 31853538, 2020). "In addition, the analysis of “The Cancer Genome Atlas” (TCGA) database shows a lower expression of the E2-synthetizing enzymes HSD17B12 and HSD17B5 (also called AKR1C3) in tumour tissue samples compared to normal tissues for UCEC." (PMID 36674737, 2023). "Women with cancer had higher expression of HSD17B12 mRNA than controls (P = .0231)." (PMID 31853538, 2020). "HSD17B12 has been identified as an oncogene in various cancers." (PMID 33118286, 2020). "Notably, HSD17B12 was also related to endometrial, ovarian, and breast cancers." (PMID 35282430, 2022). "Furthermore, the expression of HSD17B12 in CRC tissues was the highest among the pan‐cancer tissues, which indicated that HSD17B12 might play an essential role in CRC." (PMID 33118286, 2020). "Previous studies revealed that HSD17B12 could be a prognosis marker for several human cancers." (PMID 26030754, 2015). "Of these, BSG/CD147, HEBP2, HSD17B12, and GNB2L1/RACK1 have well characterised functions in cancer and cell survival." (PMID 38398114, 2024). "The enzymes in the VL-PUFA synthesis pathway, including ELOVL5, FADS2, and HSD17B12, can affect cellular arachidonic acid level and PGE2 level, and thus could change the biological activities of cancer cells in multiple stages." (PMID 36970499, 2023).